MRE11 (MRE11 double strand break repair nuclease)
Diseases named in the same sentence as MRE11 in open-access papers (continued):
Sharing a sentence is not in itself a finding about the gene and the disease.
tumor (continued). "Mice expressing hypomorphic Mre11 complex alleles recapitulate most DDR related aspects of ATM deficiency but are not tumor prone and do not exhibit the same oxygen-dependent phenotypes observed in the absence of ATM." (PMID 23532176, 2013). "Inhibiting MRE11 K673 lactylation enhances the efficacy of chemotherapy, and a small molecule peptide specifically inhibiting MRE11 K673 lactylation significantly improves the tumor‐killing effect of platinum‐based or PARP inhibitor chemotherapy in vitro and PDX models." (PMID 40443721, 2025). "Furthermore, from the IHC findings that showed both low levels of MRE11 and RAD50 were linked with higher grade tumours, the identification of aldo–keto reductase family in both RAD50 low and MRE11 low tumours highlights a role in tumour progression." (PMID 34782604, 2021). "As tumour cells overexpressing MRE11 exhibit a poor response to radiotherapy and chemotherapy and MRE11 deficiency leads to inhibition of DSB repair and enhances radio- and chemosensitivity in tumour cells, MRE11 is a potential target for increasing radio- and chemosensitivity." (PMID 31221177, 2019). "However, the correlations of MRE11 to prognosis and tumor-infiltrating inflammatory cells (TIICs) in different locations of CRC remains unclear." (PMID 32010608, 2019). "Tissue microarray analysis showed that MRE11 protein expression was increased in GC tissues (P < 0.001), and MRE11 overexpression in GC tissues was significantly related to lymph node metastasis (P < 0.05), distant metastasis (P < 0.05) and tumour-node-metastasis stage (P < 0.05)." (PMID 31221177, 2019). "Therefore our validated IHC result was intriguing, as it was anticipated that reduced expression of proteins involved in DNA repair such as MRE11 would increase patient survival after radiotherapy, through greater tumour radiosensitivity from reduced repair of DNA double-strand breaks." (PMID 24625413, 2014). "In our study, AQB was found to inhibit CBPt-induced expression of key proteins in the HRR cascade, including MRE11, RAD50, P-CHK1, P-CHK2, and RAD51, leading to DNA damage accumulation and promoting tumor cell death." (PMID 41353219, 2025). "In orthotopic mouse model, MRE11 knockdown in LN1-1 cells led to decreased total flux and reduced tumor volume of orthotopic oral tumors." (PMID 33927349, 2021). "Moreover, xenograft experiments showed that MRE11 knockdown alone did not promote tumor growth, which was consistent with previous report; while co‐knockdown of MRE11 and HP1α significantly repressed tumor growth caused by HP1α knockdown." (PMID 34363353, 2021). "In recent decade, many tumor-suppressor genes such as BRCA1, BRCA2 and BLM and downstream nucleases including XPF and MRE11 have been suggested as proteins that are important for R-loop tolerance and removal." (PMID 33857133, 2021). "Considering the roles of HP1α and MRE11 in CLIC, the repressed tumor formation was probably related with CLIC process, which strongly supports a connection between CLIC and tumorigenesis." (PMID 34363353, 2021). "Taken together, these themes support the interpretation that selection against Mre11 complex-dependent ATM signaling occurs during tumor progression, and that Rad50-dependent ATP metabolism is crucial for ATM activation by the Mre11 complex." (PMID 32187176, 2020). "The Mre11 complex and ATM govern a major axis of the DDR and several lines of evidence implicate that axis in tumor suppression." (PMID 32187176, 2020). "The expression of MRE11, RAD50 and NBS1 proteins in the TP (tumor, n = 261; normal, n = 258) were also tested, resulting in an average ROC-AUC of 0.862." (PMID 30176843, 2018).
tumor (continued). "Overall, these data indicate that MRE11 is essential for proliferation and/or survival in MYCN-driven tumor cells." (PMID 30166519, 2018). "The MRN complex comprising of DNA repair proteins MRE11, RAD50 and NBS1 (MRE11/RAD50/NBS1) detects and repairs double-strand breaks, and is therefore critical for maintaining genomic integrity and suppressing tumor progression." (PMID 29189711, 2017). "Together with MRE11 and NBS1, RAD50 is part of the MRN complex, which is heavily involved in maintenance of genomic integrity and tumor suppression." (PMID 29189711, 2017). "We analyzed the protein expression of MRE11, MDC1, ATM, ATR and BRCA1 by immunohistochemistry (IHC) in 97 SOC samples, and correlated with clinical parameters including age, tumor grades, clinical stage, status of menstruation and chemotherapy." (PMID 24752797, 2014). "The lactylated MRE11 is more likely to bind to DNA, thereby promoting the phosphorylation of ATM, and ultimately facilitating the cutting and homologous recombination (HR) at the ends of DNA, mediating the chemoresistance of tumor cells." (PMID 40399304, 2025). "Patients whose tumours had low levels of expression of BRCA2 with high levels of MRE11 co-expression had worse PFS (p = 0.005) and overall survival (p = 0.001) compared to patients whose tumours had high levels of BRCA2 with low levels of MRE11 co-expression." (PMID 37446144, 2023). "FEN1 protects perturbed forks from erroneous over-resection by MRE11 through regulating of BRCA1-RAD51 and WRN helicase, uncovering an essential genetic interaction between FEN1 and DNA-PKcs in mitigating replication-stress induced tumor genomic instability." (PMID 35414100, 2022). "Additionally, a positive correlation between the expression of MRE11 and CD44, or that of CD44 and phosphorylated AKT, was observed in OSCC tumor tissues." (PMID 35629265, 2022). "The results showed that MRE11 knockdown did not affect tumor growth significantly, while HP1α knockdown greatly enhanced it, indicating HP1α acts as a tumor suppressor in CRC." (PMID 34363353, 2021). "When MRE11, RAD50 and NBS1 were combined, we observed that survival in patients whose tumours had low MRE11/low RAD50/low RAD50 was significantly lower compared to patients whose tumours had high MRE11/high RAD50/high RAD50 expression." (PMID 34782604, 2021). "Co‐knockdown of MRE11 and HP1α greatly decreased tumor growth compared with HP1a knockdown, suggesting CLIC probably promotes tumor formation, which was induced by HP1α knockdown and then inhibited by MRE11 knockdown." (PMID 34363353, 2021). "Tumor lesions were evaluated weekly with IVIS analysis, and a significantly lower luciferase activity determined by total flux was observed at 7th and 8th weeks in MRE11 knockdown group (shMRE11) compared to control group (shLuc)." (PMID 33927349, 2021). "A significantly better tumor reduction and longer PFS was observed in MRE11- and RAD51-negative cases compared with MRE11 or RAD51 positive cases, suggesting that inhibition of these two main HR actors could improve sensitivity to chemotherapy." (PMID 34201502, 2021). "The other tested DNA sensors (Rig-I, Cgas, Sting, Ddx41, Dhx9, Dhx36, Lrrfip1, Mre11) were expressed in the tumor cells but were not significantly upregulated after irradiation." (PMID 33202881, 2020). "Overexpression of both MRE11 and ATM was also related to lymph node positivity, suggesting that the observed poor overall survival was likely due to aggressiveness and metastatic properties of the tumour cells." (PMID 30769804, 2019).
tumor (continued). "Expression levels of MRE11, RAD50 and NBS1 proteins in the TC were tested using a forward and reverse binary logistic regression analysis in an immunohistochemical scoring data set from 262 tumor samples and 258 normal tissues." (PMID 30176843, 2018). "Using ROC-AUC analysis of good versus poor histological tumor response among patients treated preoperatively with radiotherapy, the average ROC-AUC was 0.745 for the combined panel, 0.618 for ATM alone, and 0.711 for MRE11 alone." (PMID 27930716, 2016). "Our findings suggest that, after cellular exposure to HZE particles, Bcl2 may inhibit Mre11 complex-mediated DNA resection leading to suppression of the HR-mediated DSB repair in surviving cells, which may potentially contribute to tumor development." (PMID 25567982, 2015). "ATR deficiency was significantly associated with menopause (P = 0.025), strong expression of ATM (P = 0.017) and MRE11 (P = 0.040) with pre-menopausal SOC, strong expression of MRE11 (P = 0.016) with low tumor grade, and strong expression of BRCA1 (P = 0.015) with early clinical stage." (PMID 24752797, 2014). "MRE11 RNA expression was below detectable levels in eight tumours, but PCR failure was ruled out as other experiments on the same plate were successful and the result was repeated on at least one other occasion." (PMID 24625413, 2014). "MRE11 over expression, as a means to enhance repair of CPT-induced DNA damage, could be hypothesized for the CPT insensitive subset of tumor cell lines." (PMID 23056181, 2012). "Selected CRC target genes involved in apoptosis (BAX), tumor growth (TGFβRII), WNT pathway (AXIN2, TCF4, WISP3), DNA repair (ATM, ATR, BLM, BRCA1, BRCA2, DNAPKcs, MBD4, MRE11, MSH3, MSH6, RAD50, XRCC2) and PI3-kinase signaling (PTEN) were analyzed for mutations in MSI-positive HGG samples." (PMID 21637783, 2011). "MRE11 levels were moderately, but not significantly, higher in tumor tissues (p = 0.11)." (PMID 36324569, 2022). "To evaluate the expression level of MRE11 and CD44 in OSCC patients, we analyzed the two proteins by immunohistochemical staining, which showed that a positive correlation between MRE11 and CD44 protein expression was observed in OSCC tumor tissues (p < 0.001)." (PMID 35629265, 2022). "We also include an analysis of the genomic and transcriptomic landscape of the DDR PARP genes and key HR genes (BRCA1, BRCA2, ATM, RAD51, MRE11, PALB2) in GI patient tumours (n = 1744) using publicly available datasets to identify patients that may benefit from PARPi therapeutic approaches." (PMID 34440228, 2021). "Whilst we have studied a number of post-transcriptional mechanisms of MRE11 expression, we have not ruled out the possibility that transcriptional or pre-transcriptional mechanisms might be involved rarely in individual tumours." (PMID 24625413, 2014). "MRE11 was highly expressed in primary CRC and metastatic lymph node tissue compared to normal tissue, although the expression was similar in both tumor and LNM." (PMID 32010608, 2019).
infection (29 papers, 2010 to 2025). The state of being infected such as from the introduction of a foreign agent such as serum, vaccine, antigenic substance or organism. "Proteasome-mediated Mre11 loss has also been observed at late time points during infection with the small DNA tumor virus, SV40." (PMID 20949077, 2010). "Loss of Mre11 was also reported following infection by SV40, and adenovirus." (PMID 20949077, 2010). "Since the MRN complex recruits ATM to the damage site, this study used A-TLD1 patient cell lines expressing a truncated form of Mre11 to demonstrate that complete activation of ATM during infection was dependent on Mre11." (PMID 38932138, 2024). "Coupled to this L. monocytogenes also actively modulates the host DNA damage response (DDR) by triggering the degradation of the damage sensor MRE11, a process which enhances infection." (PMID 34929015, 2021). "Mre11 promoted Chk2 phosphorylation in response to both viruses by 2 h (lanes 8 and 14), indicating that, as with d109 infection, Mre11 and presumably the MRN complex were required for early recognition of incoming viral DNA." (PMID 33563816, 2021). "We observed that 24 h post infection, MRE11 was found downregulated, whereas RAD50, CTIP, and ATM were found upregulated in a CagA-independent manner." (PMID 33339161, 2020). "Infection with Ad3, Ad7, Ad11, and Ad12 resulted in relocalization of MRE11 to viral replication centers, as demonstrated by areas of RPA32 staining." (PMID 28791251, 2017). "MRN complex members colocalize with ICP8 in virus infected cells throughout infection and infections in MRE11 defective cells result in reduced viral yields." (PMID 28095497, 2017). "Although the Gluc activity of rAAV8biΔBC-Gluc was also increased in the presence of the Mre11 inhibitor, the increase was always less than that observed with rAAV8wt-Gluc 48 h post-infection." (PMID 28710345, 2017). "Cells treated with Ad-RAD50 infection, and Ad-RAD50 infection plus 4Gy IR exhibited co-localization of the signals representing wild-type Rad50 (blue) and Mre11 (red), suggesting the interaction between these two proteins (-b)." (PMID 26951044, 2016). "Strikingly, after 24 h of infection with wild type L. monocytogenes the level of Mre11 significantly decreased." (PMID 25340842, 2014). "Upon infection, MRE11 staining was increased and became localized in discrete nuclear foci around the viral DNA." (PMID 22496654, 2012). "Although we observed accumulation of Mre11 at the distinct APAR bodies early in MVM infection, we also observed that Mre11 levels were significantly diminished at late time points." (PMID 20949077, 2010). "After Ad-NBS1 infection, anti-MRE11 antibody was able to co-precipitate both NBS1 and mutant NBS1 (37 kDa)." (PMID 21063405, 2010). "We observed that levels of the Mre11 component of the MRN complex, which is associated with ATM activation, were reduced approximately 3-fold by 24 hrs following MVM infection of A9 cells." (PMID 20949077, 2010).
infection (continued). "Moreover, the Mre11 steady state levels are higher in the parental cells compared to the shIKKα knockdown cells throughout the course of infection." (PMID 40103806, 2025). "MRE11 is degraded as expected following the infection of NBS1− cells with wild-type (wt) HAdV-C5." (PMID 38140597, 2023). "In addition, the L. monocytogenes toxin LLO also acts to dampen the host DDR and promotes infection by triggering the degradation of the host DNA damage sensor MRE11." (PMID 34929015, 2021). "Finally, there was minimal exportation of MRE11 out of the nucleus following infection of cells with either an E1b55K deletion mutant Ad5 or Ad5 containing mutant E1b55K unable to bind MRN." (PMID 28791251, 2017). "Infection of HeLa cells with all three serotypes led to decreased levels of MRE11 and Rad50." (PMID 28791251, 2017). "For the rhesus macaque monkey polyomavirus SV40, infection of permissive CV1 or BSC40 monkey cells causes activation of ATM signaling, H2AX phosphorylation and Mre11-Rad50-Nbs1 assembly with T-antigen together with other DDR-signaling proteins in viral replication foci." (PMID 28202068, 2017). "Moreover, the disruption of wild-type Rad50 by infection with the mutant-Rad50 repressed the levels of wild-type Rad50, Mre11 and Nbs1." (PMID 26951044, 2016). "Furthermore, the E4orf3 and E4orf6 genes are rapidly expressed after infection to prevent the cellular DNA-damage response (DDR) mainly by inactivating the Mre11-Rad50-Nbs1 (MRN) complex." (PMID 26872382, 2016). "Likewise, in the case of Listeria, we show that downregulation of Mre11 or ATM or H2AX favors infection." (PMID 25340842, 2014). "Mre11 degradation has only been shown to occur during infection with a virus." (PMID 25340842, 2014). "Indeed, infection with adenovirus has been shown to result in both reorganization and degradation of members of the Mre11–Rad50–NBS1 complex." (PMID 25340842, 2014). "Using a combination of immunohistochemistry and FISH, we determined whether MRE11 localized with PyV DNA during infection." (PMID 22496654, 2012). "In agreement with viral hindrance of the Mre11/MRN function, both AdΔ19K- and Ad5-infection decreased the potent activation of pChk1 in drug-treated cells suggesting checkpoint abrogation." (PMID 26872382, 2016). "At 24 h after infection with Ad-RAD50, the Mre11 and Nbs1 proteins were also significantly downregulated in cells treated with Ad-RAD50 alone or combing with 4Gy IR." (PMID 26951044, 2016). "To understand the mechanism by which LLO dampens the DDR we investigated the effect of infection and the effect of the purified LLO toxin on the host proteins, Mre11, RAD50 and NBS1, involved in sensing DNA breaks." (PMID 25340842, 2014). "We infected mouse embryonic fibroblasts (MEFs) from Mre11ATLD mice, in which the mre11 gene is truncated, with L. monocytogenes expressing GFP and compared, infection of these cells to infection of wild type MEFs by FACS analysis." (PMID 25340842, 2014). "It appears that during infection with Ad5, MRN is first localized to the nuclear tracks, where it binds E1B-55K, and later, either E4orf3 or E4orf6 as well as E1B-55K are required for E1B-55K aggresome formation, and Mre11 is exported to the aggresomes." (PMID 32906746, 2020). "This yet unproven hypothesis is supported by the finding that DDR sensors and effectors such as Mre11, Mdc1, and ATM colocalized with viral genomes early during infection." (PMID 32906746, 2020).